KEAP1 (kelch like ECH associated protein 1)
Diseases named in the same sentence as KEAP1 in open-access papers (continued):
Sharing a sentence is not in itself a finding about the gene and the disease.
cancer (continued). "Additionally, cancer cells acquire novel nutrient dependencies to support oncogenic growth by changing metabolic pathways, Sarah E first points that dietary restriction or enzymatic depletion of asparagine can lead to suppression of Keap1 mutant tumor growth." (PMID 32576270, 2020). "Further, the anti-oxidant Keap1/Nrf2/ARE pathway could play a crucial role in mitigating oxidative stress, leading to a reduction of chronic inflammation linked to the prevention of cancer." (PMID 32823757, 2020). "Furthermore, epigenetic reprograming of NRF2 can lead to its reactivation and subsequent induction of downstream target genes involved in cellular protection, further suggesting the use of KEAP1 within the NRF2 pathway as a potential target for cancer treatment." (PMID 33143142, 2020). "Interestingly, KEAP1 is frequently inactivated in NSCLC (about 20% of cases), and LKB1-defective tumors have more than sixfold increased odds of bearing KEAP1 loss compared to LKB1-proficient cancers." (PMID 31781355, 2019). "Genetic alterations in KEAP1, NRF2, and CUL3 such as somatic mutations, copy number variations, and epigenetic changes are the major reasons for the gain-of-function and aberrant activation of NRF2-regulated pathways in human cancers and are often correlated with poor prognosis and survival." (PMID 31884422, 2019). "An important mechanism of cellular ROS clearance relies on the Keap1-Nrf2 pathway, which has been well characterized especially in the context of cancer biology; however, the upstream signaling molecules that could regulate the Keap1-Nrf2 axis in OCs remains unknown." (PMID 31490121, 2019). "We therefore next investigated whether or not K‐563 inhibited the Keap1/Nrf2 downstream gene expression and exerted cell growth inhibition in other Keap1‐ or Nrf2‐mutated human cancer cell lines." (PMID 30735010, 2019). "Collectively, these data suggest that the overexpression of different types of ETGE-containing proteins in cancer cells might sustain NRF2 activity even in the absence of activating mutations in the NRF2 or inactivating mutations in the KEAP1 genes." (PMID 31097977, 2019). "Possible causes of such a constitutive stabilization of Nrf2 molecules could be the mutations in the Nrf2 or Keap1 genes, already identified in many types of cancer, or the accumulation of proteins that interfere with Keap1-Nrf2 interactions, such as p62 and p21." (PMID 30978928, 2019). "Keap1 or Nrf2 independent mutations in oncogenes, including EGFR, Kras, Braf, Myc, and the Bcr-Abl fusion may also increase Nrf2 levels, resulting in ROS detoxification and chemo-resistance in cancer." (PMID 31022969, 2019). "In the same way, the loss of KEAP1 by the CRISPR-Cas9 system cooperates with the tumor mutational landscape in modulating the response to BRAF, MEK, EGFR, and ALK inhibition and in allowing cancer cells to increase their ability to resist to treatments and proliferate." (PMID 29643973, 2018). "Consequently, the Keap1–Nrf2 system is extensively pursued for the development of protein–protein interaction inhibitors that will stabilize Nrf2 for therapeutic effect in conditions of neurodegeneration, inflammation, and cancer." (PMID 26057936, 2015). "Interestingly, a novel class of Keap1 cancer mutations have recently been identified which do not lead to the destruction of two-site binding." (PMID 24681086, 2014). "Because Nrf2 exhibits protective effects against oxidants and electrophiles in normal cells but sustained Nrf2 activation favor the growth of tumors, it is possible to speculate that differential epigenetic regulation of Nrf2 and/or Keap1 might exist in normal and cancer cells." (PMID 25014534, 2014). "While KEAP1 mutations are frequent in other cancers, they are not in PTC." (PMID 24138990, 2013).
cancer (continued). "Taken together, epigenetic modifications of the NRF2/KEAP1 axle are predicted to cause dysregulation of ARE-mediated cellular defense leading to deleterious health effects, and phytochemical antioxidants as epigenetic modulators for NRF2 are suggested to be useful in cancer prevention." (PMID 23936606, 2013). "Thus, p62 expression similar to Nrf2 activation or Keap1 inactivation may enhance antioxidant defense and cancer cell survival." (PMID 22848625, 2012). "Mutations in KEAP1 or NRF2, which abrogate formation of the complex and lead to NRF2 accumulation and constitutive upregulation of the pathway, have been detected in several types of human cancer, including cancer of the lung, oesophagus, ovary, gallbladder, and skin." (PMID 24278719, 2012). "Enhancing the interaction between KEAP1 and NRF2 at the protein level holds promise as a valuable approach in cancer therapy." (PMID 39744483, 2025). "Heatmap results showed that NRP1, MFAP2, KLC1, DST, and MYOZ3 were generally downregulated in cancer cell lines, while KIF21B, SRI, INCENP, and KEAP1 were also downregulated." (PMID 40228435, 2025). "The KEAP1/NRF2 axis, by virtue of its antioxidant and cytoprotective effects, is a double-edged sword in cancer treatment." (PMID 41462606, 2025). "Because triterpenoids have a cancer cell mutation-agnostic decrease in macrophage CD206 and increased lymphoid activation, this strengthens support for their potential clinical utility and would indicate KEAP1-mutant treatment-resistant cancers may still benefit from triterpenoid therapy." (PMID 41462606, 2025). "Beyond cancer, NRF2/KEAP1 signaling is critically involved in the pathogenesis of several chronic diseases, including neurodegeneration, metabolic syndrome, and cardiovascular disease, highlighting its dual role in cytoprotection and disease progression." (PMID 40867889, 2025). "Next, we bilaterally transplanted the KEAP1-KO and DKO cancer cells into both flanks of immunocompetent mice." (PMID 41035689, 2025). "As a result, the KEAP1/NRF2 pathway has garnered significant interest as a therapeutic target, with both activators and inhibitors of this axis showing potential in cancer treatment strategies." (PMID 39859211, 2025). "Molecular docking studies confirmed stable binding interactions (binding energies: –4.9 to –6.8 kcal/mol) of BITC and CA with key cancer-related proteins (ERK2, p38 MAPK, Bcl-2, Keap1-Nrf2, GST)." (PMID 40799801, 2025). "Recent studies suggest that KEAP1/NRF2 alterations in NSCLC serve as biomarkers of poor prognosis and contribute to resistance to various cancer treatments, such as chemotherapy, radiotherapy, immunotherapy, and TKI therapy." (PMID 40510148, 2025). "The difference in cellular responses complicates the prediction of outcomes when treating a KEAP1-mutant cancer with an NRF2-activator like CDDO-Me, since the known NRF2 effects on cancer and immune cell biology are opposing." (PMID 41462606, 2025). "Cancer cells often develop resistance to chemotherapy and ferroptosis by stabilizing NRF2 through KEAP1 inactivation or genetic alterations in the NRF2 pathway, with NRF2 overexpression associated with poor outcomes in primary malignant brain tumors." (PMID 39935430, 2025). "Heatmap of the RNA-seq data for the culture cells indicates that expressions of Il7, Serpinb9e, and Slpi genes were significantly upregulated in KEAP1-KO cancer cells, but were downregulated in DKO cancer cells." (PMID 41035689, 2025). "In cancer, NRF2 is well-known for regulating oxidative stress, mostly in the context of KEAP1-mutant cancers." (PMID 41372143, 2025). "Further validation in four independent cohorts showed that KEAP1, SRI, MFAP1, MFAP2, INCENP, and KIF21B were consistently upregulated in cancer tissues, while MYOZ3, DST, and TIAM1 were consistently downregulated." (PMID 40228435, 2025).
cancer (continued). "To gain mechanistic insights as to how NRF2 activation in cancer cells induces low immune cell infiltration into tumor tissues, we investigated changes in gene expression in WT, KEAP1-KO, and DKO cancer cells." (PMID 41035689, 2025). "Other tumor suppressor genes (KEAP1, STK11), which can impair immunotherapy responses in KRAS-mutant cancers, showed slightly increased frequency from baseline to progression." (PMID 40244261, 2025). "The KEAP1/NRF2 pathway, a major regulator of the cellular oxidative stress response, is frequently activated in human cancers." (PMID 41573641, 2025). "This analysis revealed that transcript levels from KEAP1 inversely correlated with ARID1A, albeit mildly, across a pan-cancer panel (n = 10,071, r = −0.12, p = 2.2 × 10−16)." (PMID 39272807, 2024). "Mechanistically, we find that 4-OI suppresses antiviral immunity in cancer cells through the modification of cysteine residues in MAVS and IKKβ independently of the NRF2/KEAP1 axis." (PMID 38750019, 2024). "Nrf2/Keap1/ARE pathway activation also leads to enhanced chemoresistance and radioresistance in cancer cells." (PMID 39407193, 2024). "KEAP1 mutant NSCLC is highly refractory and resistant to traditional cancer treatments, such as radiotherapy, chemotherapy, and targeted therapy." (PMID 38521813, 2024). "Keap1 can also function as an IKK β, the role of E3 ligases that inhibit NF-κB expression of the pathway, which in turn inhibits cancer initiation." (PMID 38634043, 2024). "In line with the findings, deletion of Keap1 and PTEN leads to higher levels of Nrf2 levels within cancer cells." (PMID 39407193, 2024). "Inhibition of miR-141-3p promoted Keap1 expression, inhibited Nrf2 and its downstream SLC7A11-GSH-GPX4 signaling pathway, as well as promoted ferroptosis in cancer cells, and inhibited paclitaxel and RSL3 resistance." (PMID 39308683, 2024). "In contrast, the KEAP1/NFE2L2 pathway is involved in managing cellular stress and can shield cancer cells from the impact of radiation therapy." (PMID 38741207, 2024). "Our data suggest that targeted inhibition of miR-141-3p promoted Keap1 expression and suppressed Nrf2 expression and inhibited SLC7A11-GSH-GPX4, the downstream anti-ferroptosis pathway of Nrf2, in cancer cells." (PMID 39308683, 2024). "More than 600 somatic mutations in the NFE2L2 gene have been identified across various cancers, with the majority affecting the DLG and ETGE motifs, abolishing the interaction of Nrf2 with KEAP1." (PMID 39769005, 2024). "Moreover, Keap1 works as a E3 ligase of IKKβ, since it has an ETGE-Motif-NQE36TGE39- homologous to the one present in the Nrf2 protein, so KEAP1 is considered as a IKKβ interacting protein and mutations or alterations in Keap1 gene are correlated with cancer or a deeply altered cell stress response." (PMID 37640833, 2024). "CAT and GSTP1 genetic variability was thoroughly studied in oxidative-stress-related diseases, especially different types of cancer, while in neurodegeneration, NFE2L2 and KEAP1 have recently gained the interest of researchers." (PMID 36829875, 2023). "Notably, the loss of function of Keap-1 rendered cancer cells sensitive to NEAA (including Asn) restriction in preclinical animal models, suggesting that combining L-ASP and ICB may be a promising strategy to treat NSCLC with Keap-1 mutations." (PMID 37550596, 2023). "When the Keap1/NRF2 pathways, influenced by cancer-promoting signals, become disrupted in cancer cells, there is a surge in the transcription and translation of NQO1." (PMID 38264080, 2023). "These regulatory mechanisms shed light on the complex regulation of FSP1 in cancer, highlighting the involvement of NRF2, KEAP1, and NAT10 in modulating FSP1 expression and activity in the context of ferroptosis and therapeutic responses." (PMID 37371948, 2023).
cancer (continued). "Considering the promising role of NRF2/KEAP1 signaling pathway activation in protecting cells from ROS and its potential for use in cancer treatment, this study aims to identify natural products that can modulate the NRF2/KEAP1 pathway." (PMID 37630254, 2023). "Treatment with this SCFA inhibited cancer cell growth by driving metabolic rewiring and epigenetic reprogramming, involving a decrease in NRF2, an increase in the NRF2 negative regulator Keap1, and inhibition of NRF2-target genes, such as as NQO1." (PMID 36986408, 2023). "In line with these gene expression results, we observed that Keap1-KO BMDMs fully replicated the growth- and matrix invasion–promoting effects of heme-TAMs in MC38 cancer cell spheroids." (PMID 38060331, 2023). "Specifically, the molecules involved in cancer-related pathways, including LAMB3, KEAP1, Bid, EGFR, Bcl-XL, Bcl-2, and PAX8, were all regulated by JorA." (PMID 37587470, 2023). "As the Keap1/NRF2 axis is disrupted in various cancers, it is a potential therapeutic target for cancer and chemoresistance." (PMID 37108769, 2023). "Hypermethylation of the KEAP1 promoter and resulting downregulation of KEAP1 expression levels represent another relevant mechanism leading to a constitutive NRF2 activation in cancer." (PMID 36289675, 2022). "Apart from different cancer stages, it is also critical to consider the temporal nature of NRF2/KEAP1 signaling." (PMID 35754474, 2022). "In particular, it regulates the Keap1/Nrf2/ARE pathway and promotes antioxidant and apoptotic effects in cancer cells." (PMID 36501112, 2022). "Previous studies indicated activation of the ROS-scavenging signal (e.g., Keap1-Nrf2-ARE pathway) and deregulation of anti-oxidant enzymes (PRDX, GPxs, TrxRs, and MnSOD) in CP-resistant cancer cells 50-52." (PMID 35541901, 2022). "Kelch-like epichlorohydrin-related protein 1 (Keap1), a member of the BTB-Kelch protein family, has been reported as an important molecule in several cancers." (PMID 34466284, 2021). "Recent studies demonstrated that KEAP1/NRF2 axis dysfunction is strongly related to tumor progression and chemo- and radiotherapy resistance of cancer cells." (PMID 34247575, 2021). "Under normal or low/moderate stress conditions, there is a tight balance between KEAP1 activity and NRF2 protein levels, which provides regulated antioxidant response, detoxification, and prevention of cancer." (PMID 33808001, 2021). "Several studies concluded that KEAP1 and NRF2 levels can be regulated at the post-transcriptional level in different cancers by abnormal expression of miRNAs targeting these genes." (PMID 33808001, 2021). "Subsequently, circKEAP1 was confirmed to act as a sponge of mir-141-3p, relieve the inhibition of miR-141-3p on its target gene KEAP1, and activate KEAP1/NRF2 signaling pathway, thereby inhibiting cancer cell proliferation and migration." (PMID 34136401, 2021). "KEAP1 and HOMOX1 were low expressed in tumor than the para-carcinoma tissues, and the high expression of these two genes increased the risk of FRPS, which suggested the poor prognosis of patients." (PMID 34692692, 2021). "Epigenetic modifications seem to control the expression of KEAP1/NRF2 system and therefore it is important to investigate this type of regulation in cancer." (PMID 32106613, 2020). "In HepG2 cells, BAI was shown to target Keap1 to stimulate ubiquitination and modification of Keap1, leading to the activation of NRF2, cytoprotection and cancer chemoprevention." (PMID 32526964, 2020). "For its clinical significance in cancers, we then detected the expression levels of TRIM25, Keap1 and Nrf2 in cancerous and paired adjacent tissues from 90 HCC patients." (PMID 31953436, 2020).
cancer (continued). "It was revealed that the anti-cancer activity of SFN is modulated by a variety of cell-signaling pathways including NF-κB signaling, Keap1– Nrf2 signaling, and ROS-dependent pathway." (PMID 32309226, 2020). "In many cancers, the NRF2 and KEAP1 will undergo hypermethylation, leading to a repression of expression of the KEAP1 protein and the release of NRF2." (PMID 33143142, 2020). "However, over 50% of the cancer tissues without Keap1 mutations still showed a high Nrf2 activity." (PMID 32047536, 2020). "In cancer, miRNAs can affect the cellular redox homeostasis by targeting genes involved in the NRF2/KEAP1 regulatory system." (PMID 31717786, 2019). "Despite that these stimuli are well-known and prototypical inducers of the NRF2/KEAP1 pathway, accumulating evidence indicates that proinflammatory conditions or nutrient withdrawal can also activate NRF2 in cancer cells." (PMID 31097977, 2019). "Recent studies demonstrated that KEAP1/NRF2 axis dysfunction is also strongly related to tumor progression and chemo- and radiotherapy resistance of cancer cells." (PMID 29643973, 2018). "Inactivation of KEAP1 strongly induces NRF2, and this phenomenon is often observed in cancer cells; cancer cells can thus acquire malignancy by perverting NRF2 activity." (PMID 28523248, 2017). "In particular, Keap1, KLHL20, and SPOP are the most reported Cul3 substrate adaptors for their impacts on various cancer types." (PMID 27200299, 2016). "Finally, frequent cooccurring mutations NFE2L2, KEAP1, and NOTCH1 in a study on more than four thousand human cancers support the notion that the outcome from aberrant Nrf2–Notch crosstalk by mutations in these genes might specifically enhance tumorigenesis and progression to cancer." (PMID 27847554, 2016). "Therefore, high levels of sustained NRF2 activity, which would occur following KEAP1 loss or mutation but not following pharmacological inhibition of KEAP1, may be required to provide a growth or survival advantage to some cancer cells." (PMID 26301506, 2015). "We reasoned that RTA 405 would be unable to increase NRF2 activity in cell lines with low or mutant KEAP1; however, the status of KEAP1 and the basal activity level of NRF2 has been reported for very few common cancer lines." (PMID 26301506, 2015). "We found that basal levels of other cancer-related KEAP1 targets, IKKβ and BCL2, were elevated in Keap1-/- MEFs and in human tumor lines with high basal NRF2 activity." (PMID 26301506, 2015). "Considering Keap1-Nrf2-ARE and IKKβ-NF-κB pathways play contrary roles in the pathological processes of inflammation and cancer, the interference of NF-κB signaling and Nrf2-ARE pathway is vital to maintain the balance." (PMID 24066166, 2013). "Several target genes of miR-200a have been identified by comparing normal and cancer epithelial cells, such as ZEB1, ZEB2, SIRT1, and KEAP1." (PMID 23750238, 2013). "Keap1-knockdown and then Nrf2 activation resulted in dramatic induction of human CBR3 in cancer cell lines." (PMID 22808024, 2012). "The inhibition of KEAP1 gene expression results in NRF2 accumulation, conferring a survival and growth advantage to cancer cells." (PMID 23272301, 2012). "Although the proposed glue-like mechanism remains hypothetical, this work supports further investigation into the NRF2-KEAP1 interaction and may inform the development of KEAP1-targeted strategies for NRF2Mut cancers, including ESCC." (PMID 42122150, 2026). "Independent of KEAP1/NRF2/CUL3 mutations, altered protein-protein interactions and KEAP1-inactivating posttranslational modifications also activate NRF2 in cancer, most notably in tissues of the liver, breast, and kidney." (PMID 40889681, 2025).